CTLA4 (cytotoxic T-lymphocyte associated protein 4)
Diseases named in the same sentence as CTLA4 in open-access papers (continued):
Sharing a sentence is not in itself a finding about the gene and the disease.
tumor (continued). "Tremelimumab (Imjudo, AstraZeneca, Inc.)is a human monoclonal antibody, approved by the FDA and EMA, that blocks the activity of CTLA-4 and thus activates the anti-tumor immune response." (PMID 38384472, 2024). "Unlike FPT155, ALPN-202 is a mutated CD80-Fc fusion protein designed to overcome checkpoint inhibitor resistance by enhancing CD28 costimulation in the tumor microenvironment while inhibiting PD-L1 and CTLA-4." (PMID 39575257, 2024). "In particular, the expression profile of immune regulatory molecules such as PD-1 or CTLA-4 and the number of Treg cells were found to be comparable, ultimately delaying tumor development." (PMID 38986222, 2024). "After the cancer mass was established, CIRT was performed only on the right leg tumor, followed by a systemic injection of ICIs against CTLA4 or PD-LA." (PMID 38474078, 2024). "Therapeutic antibodies, such as ICIs, function by blocking homeostatic signals, such as CTLA-4 and PD-1, with the aim of triggering immune responses against tumor cells." (PMID 38464532, 2024). "Further, neo VAX used in combination with anti-CTLA-4 or anti-PD-1 provided superior tumor growth inhibition compared to combination anti-CTLA-4 and anti-PD-1 ICT." (PMID 38187708, 2024). "Several checkpoint molecules, namely PD-1 on T cells, PD-L1 on tumor cells, and CTLA-4 on antigen-presenting cells or tumor cells, are most frequently researched in human cancer." (PMID 38893154, 2024). "Tregs co-cultured with exosomes derived from tumor cells also showed high expressions of Fas-L and CTLA-4, ably inhibiting the function of CD8+ T cells." (PMID 38685033, 2024). "In contrast, both RMC-4998 or RMC-4550 displayed increased anti-tumour activity and induced occasional CRs when combined as single agents with anti-CTLA-4." (PMID 39322643, 2024). "In cancer, tumor cells evade the immune system by expressing CTLA-4, allowing the tumor cells to inhibit the immune response and continue growing and spreading throughout the body." (PMID 39343796, 2024). "Initially, we probed the expression levels of CD86 and CD80 essential molecules for CTLA-4 interaction on tumor cells." (PMID 38473398, 2024). "Taken together, these data demonstrate that anti-CTLA-4 Ab can exert its anti-tumor effects through Th1-mediated cell cycle arrest and apoptosis." (PMID 39106430, 2024). "Cytotoxic T lymphocyte antigen 4 (CTLA4) is a common target of T cells with high expression in tumor patients, which can bind to B7 ligand on tumor cells to inhibit T cell activity." (PMID 38582791, 2024). "In high-throughput genetic screening, the ICB treatment process in cancer patients is simulated by implanting gene-edited tumor cells in mice and administering anti-PD-1 or anti-CTLA-4 intravenously." (PMID 39538305, 2024). "The main types of ICB therapy include PD-1/PD-L1 inhibitors and CTLA-4 inhibitors, which block immune checkpoint proteins, allowing the immune system to recognize and attack tumor cells." (PMID 39221221, 2024). "Nevertheless, combining immune checkpoint (e.g., CTLA-4 and PD-1) blockers has a synergistic effect in increasing the patient response by activating anti-tumour immune responses in dual pathways." (PMID 39000359, 2024). "In conclusion, the inhibition of (CTLA-4)-related lncRNAs can effectively disrupt the nutrient supply to tumor tissue, thereby inhibiting tumor growth." (PMID 39143529, 2024). "The combination of CTLA-4 and PD-1 ICIs resulted in tumor rejection in 50% of the mice, more than doubling the efficacy of using either ICI alone." (PMID 39068460, 2024). "We have a preliminary understanding of the correlation between CTLA-4 related lncRNAs and tumor progression and the mechanism." (PMID 39143529, 2024). "In cancer immunotherapy, ICIs, by targeting CTLA-4 or interrupting the PD-1/PD-L1 interaction, can restore immune activity, thereby exerting an anti-tumor effect." (PMID 39068460, 2024).
tumor (continued). "Although CTLA-4 is a relevant target for enhancing effector responses in some tumor models, blockade of CTLA-4 leads to enhanced costimulatory signals and hyperproliferation of Treg cells, resulting in increased immune tolerance." (PMID 39795946, 2024). "The tumor cell killing assay revealed that each of the individual ligands, except for the CTLA-4 antibody, demonstrated appreciable increases in tumor cell killing." (PMID 39033322, 2024). "Recently, a number of preclinical investigations have demonstrated that the efficacy of CTLA-4 antibody drugs relies on the elimination of Treg cells within the tumor, facilitated by the antibody’s heavy chain constant region Fc and immune cell Fc receptors." (PMID 38380323, 2024). "In malignancies, CTLA-4 expressed by tumour cells is supposed to facilitate tumour cell evasion by ablating the immune surveillance of immune cells (ICs) around the tumour because CTLA-4 inhibition results in increased activation of the immune system." (PMID 39286684, 2024). "In the context of cancer, blocking CTLA-4 with ipilimumab or tremelimumab enhances the activity of effector T cells, which can lead to a more robust anti-tumor response." (PMID 39682686, 2024). "On the basis of such assessments of therapeutic effects, some studies have proposed the concept of using novel bispecific antibodies to target PD‐L1 and CTLA‐4 immune checkpoints in order to produce synergistic anti‐tumor effects." (PMID 39032129, 2024). "CTLA-4 is upregulated in tumor-specific T cells and acts as an “off” switch when it binds CD80 (B7-1) or CD86 (B7-2) on the surface of cancer cells." (PMID 38893211, 2024). "Combination therapy with bicarbonate and anti-PD1 or anti-CTLA-4 impaired tumor growth and led, in some cases, to tumor regression." (PMID 38398062, 2024). "But a variety of tumor cell types have the ability to stimulate CTLA‐4 in the tumor's microenvironment, which enables the tumor cells to avoid being recognized and eliminated by the immune system by early suppressing T lymphocytes." (PMID 38571678, 2024). "Strong synergistic effects have been observed when combining GM-CSF immunization with anti-PD1 or CTLA4 blockade in various tumor models." (PMID 39041242, 2024). "We observed an expansion of CD4+ T helper and CD8+ T cytotoxic cell populations in TDLNs as well as enhanced tumor infiltration in the 16 Gy + anti-CTLA4 arm." (PMID 39199612, 2024). "Tremelimumab, a human IgG2 monoclonal antibody against CTLA-4, was given at a dosage of 15 mg/kg once every 3 months to 21 HCV-associated HCC patients until tumor progression." (PMID 38999940, 2024). "The top candidates were further corroborated using transcriptomic data obtained from tumor samples in a cohort of patients that were administered either PD1 inhibitor or CTLA4 inhibitor therapies." (PMID 39015503, 2024). "Previous work has indicated that tumor glycolysis confers resistance to CTLA-4 blockade, while tumor cell oxidative metabolism is a mechanism of resistance to αPD-1 therapy." (PMID 39225102, 2024). "Tregs are one of the major cells capable of inducing dysfunction in DCs through the expression of high-affinity CD80 and CD86 ligands, cytotoxic T-lymphocyte-associated antigen 4 (CTLA-4), which competes with CD28 on T cells and limits tumor immunogenesis." (PMID 38927447, 2024). "Our analysis of CTLA-4 mRNA level within human tumor samples showed significant positive correlations between isoforms, and membrane-bound CTLA-4 is the predominant isoform." (PMID 38053333, 2024). "Subsequently, in a subcutaneous transplantation tumor model using Foxp1-deficient LLC cells treated with anti-CD47 Ab, it was observed that Foxp1 deletion partially prevented the increase in the CTLA4 level induced by anti-CD47 Ab treatment." (PMID 38398223, 2024).
tumor (continued). "In the same study, the inclusion of conventional HDRT (12 Gy) targeted at a single tumour significantly heightened the therapeutic effectiveness of low-dose TRT when delivered in conjunction with CTLA-4." (PMID 38833685, 2024). "ICIs are a form of immunotherapy that has garnered significant attention in recent years for their potential in tumor treatment by targeting and inhibiting immune checkpoints, such as CTLA-4 and PD-1, to activate the immune response." (PMID 39055561, 2024). "Upon CTLA-4 activation, T cell activation and IL-2 secretion are diminished, exerting a negative regulatory effect on tumor immunity." (PMID 39290709, 2024). "The group treated with α-CTLA-4 12 h after radiation had a significantly lower tumor burden at day 22 compared to the α-CTLA-4 only group." (PMID 38240876, 2024). "ICIs are monoclonal antibodies that can target and block immune checkpoints, such as PD-1 and CTLA-4 on T cells or PD-L1 on tumor cells, thus inhibiting tumor immune escape and enhancing the antitumor function of T cells." (PMID 39840031, 2024). "The limited peripheral distribution reduces treatment-associated on-target off-tumor toxicity, and the preclinical study has demonstrated that the toxicity of KN046 is lower than that of the anti-CTLA-4 inhibitor." (PMID 38310192, 2024). "The use of ICIs can directly influence and target Tregs, as CTLA4 is constitutively expressed on naïve Tregs and at higher levels on effector Tregs and on tumor-infiltrating Tregs." (PMID 38611115, 2024). "We postulate that the therapeutic response by 16 Gy + anti-CTLA4 was attributed to this mode of IR-induced anti-tumor immunity." (PMID 39199612, 2024). "The depletion of CD4+ T cells prevented anti-tumor effects of the anti-CTLA-4 Ab, whereas depletion of CD8+ T cells had little effect in the Hepa1-6 model." (PMID 39106430, 2024). "In the T-cell activation process, lysosomes can enhance the degradation or transport of immune checkpoint molecules like PD-1, PD-L1, and CTLA4, reducing immune evasion by tumor cells." (PMID 38370407, 2024). "Recent research shows tumor exhibiting mesenchymal‐like is T cell‐excluded with CTLA4 blockade resistance compared with epithelial‐like tumor, indicating EMT is a significant player in the resistance to immunotherapy." (PMID 39092293, 2024). "The co-involvement of these two distinct cellular mechanisms has led to the clinical observation that combining anti-CTLA-4 with anti-PD-1 therapy enhances anti-tumour efficacy." (PMID 38475858, 2024). "After the activation of CTLA-4, the transmission of tumor antigens from DC cells to T cells is hindered, resulting in the inability of T cells to identify and eliminate tumor cells." (PMID 39122457, 2024). "Perinatal mice‐human CTLA‐4 knock‐in mice display rapid tumour regression in response to ipilimumab, coupled with severe organ inflammation in heart, lung, liver and kidney." (PMID 38963257, 2024). "The increased interaction among CD80, PD-L1, and CTLA-4 presents a new concept for anti-tumor immunotherapy." (PMID 39575257, 2024). "The ACC tumour microenvironment shows low levels of CD8+ tumour infiltrating lymphocytes, PD‐1 and cytotoxic T lymphocytes antigen 4 (CTLA‐4) positive cells and overexpresses immune inhibitors such as PD‐L2, but not PD‐L1." (PMID 39324702, 2024). "Conversely, CTLA-4 inhibitors obstruct the CTLA-4 molecule on the surface of inhibitory tumor immune cells, bolstering the activity of immune effectors." (PMID 39234260, 2024). "Building on these findings, our results showcased that the treatment of tumors by high-dose radiotherapy alone effectively functions as in situ vaccination, which promoted the anti-tumor T-cell response in combination with anti-CTLA4." (PMID 39199612, 2024). "Classical inhibitors targeting PD-1 and CTLA-4 largely exert their anti-tumor effects by mitigating functional exhaustion." (PMID 38629071, 2024).
tumor (continued). "The most common ICBs refer to blocking immune inhibitory receptors CTLA4 and PD‐1 on T cells, or PD‐L1 on tumor cells and tumor‐infiltrating immune cells using antagonistic antibodies." (PMID 38233204, 2024). "A correlation between KRAS and CTLA-4 mRNA expression in CTCs and primary tumor tissues was observed, suggesting a potential role of CTLA-4 in KRAS-mediated CRC progression." (PMID 39539964, 2024). "The combination of Tranilast and Doxil also significantly increased the levels of immunostimulatory M1 macrophages in tumor tissue, enhancing the efficacy of immune checkpoint inhibitors (such as anti-PD-1/anti-CTLA-4)." (PMID 39534084, 2024). "In preclinical models, tumor-derived exosomes have been shown to impair CAR T cell function by increasing inhibitory receptors such as CTLA4 and TIM-3, hindering antigen-specific CAR T cell proliferation and cytotoxicity." (PMID 39684867, 2024). "Accordingly, targeting the CTLA-4 pathway, often used in tumor immunotherapy, leads to multi-organ autoimmune reactions." (PMID 39359726, 2024). "Based on the knowledge that ceramides influence the immune response in the tumor microenvironment, combining nanoliposome C6-ceramide with the anti-CTLA4 antibody have shown improved anti-tumor immunity in hepatocellular cancer." (PMID 38599378, 2024). "ICIs, exemplified by monoclonal antibodies, targeting PD-1 (such as pembrolizumab and nivolumab), PD-L1 (like atezolizumab, durvalumab, and avelumab), and CTLA-4 (such as ipilimumab), have demonstrated sustained efficacy across various tumor types." (PMID 38893132, 2024). "Within T cells, TRAF6 facilitates the ubiquitination of CTLA-4 at Lys63 sites, consequently fostering CTLA-4 degradation through the lysosome, ultimately enhancing anti-tumor immunity." (PMID 39223632, 2024). "This innovative strategy obstructs both CTLA-4/B7 and PD-1/PD-L1 pathways, significantly bolstering the anti-tumor immune assault." (PMID 38735927, 2024). "Combining IL-15 with PD-L1 and CTLA-4 blockade has been shown to improve antitumor immunity, slow tumor growth, and prolong animal survival in several preclinical studies." (PMID 39507777, 2024). "In preclinical studies, radiation and chemotherapy have been observed to up-regulate the expression of immune checkpoints in tumor-associated lymphocytes, including PD-1, TIM-3, and CTLA-4." (PMID 38294629, 2024). "CTLA-4 exerts a negative regulatory effect on T cells, and its blockade can inhibit tumor formation, making it useful in cancer IT." (PMID 39273605, 2024). "Immune checkpoint inhibitors (ICIs), such as PD-1/PD-L1 and CTLA-4, restore and enhance the body’s immune surveillance and attack ability against tumors by relieving the inhibition of tumor cells on the immune system." (PMID 39850905, 2024). "The combination of MEK inhibitors with PD-1 inhibitors and CTLA-4 inhibitors has synergically promoted durable tumor regression and longevity of tumor-infiltrating CD8+ T cells to provide additional efficacy in preclinical mouse models." (PMID 38600471, 2024). "This approach provides information on tumor immune responses across focal areas, treatment stages, and tumor progression directly by monitoring immune biomarkers such as CTLA-4, PD-1/L1, HER2, and MHC molecules." (PMID 38816871, 2024). "Here, we compared effective therapeutic tumor-specific mutant neoantigen (NeoAg) cancer vaccines with anti-CTLA-4 and/or anti-PD-1 ICT in preclinical models." (PMID 38187708, 2024). "Anti-PD1 therapy has emerged as a leading form of ICB therapy, outperforming the anti-CTLA4 therapy in various tumor types." (PMID 39044839, 2024). "PDCD1 and CTLA4 were scattered sporadically in the tumor region with T cell aggregation, and they were more widely distributed in the CA group than the NC group." (PMID 39256364, 2024). "Up-regulation of PD-1 and CTLA4 inhibits T-cell activation and proliferation, allowing tumours to evade immune recognition and elimination." (PMID 38546385, 2024).
tumor (continued). "On day 9 after tumor inoculation, we observed reduced expression of CTLA-4, KLRG1 and ICOS in Il23r-KO Treg cells." (PMID 38356059, 2024). "Analysis of the IRS within the tumor showed that the immune-high subtype was characterized by significantly higher levels of CTLA-4 expression in cancer cells compared to the immune-low subtype (Mann–Whitney test p < 0.0001)." (PMID 38611048, 2024). "When CTLA-4 binds to its ligand, it reduces the activation of the cytotoxic T-cells and suppresses the immune response to tumours." (PMID 38893123, 2024). "Another study demonstrated that anti-CTLA-4 combined with DNA vaccines also had synergistic effects, resulting in significant tumor regression compared to anti-CTLA-4 monotherapy." (PMID 38956700, 2024). "Unfortunately, the present method, which resolves tumor escape from host defense, also impairs the immune tolerance checkpoint, resulting in severe irAEs, especially when combined with anti-CTLA-4 antibodies." (PMID 38165484, 2024). "Immune checkpoints such as PD-1, PD-L1, and CTLA-4 are believed to assist tumor cells in evading the immune destruction by CD8+ cytotoxic T cells." (PMID 39087027, 2024). "IL-21 combined with PD-1 or CTLA-4 monoclonal antibodies can slow down tumor growth and increase CD8 + T-cell proliferation and infiltration." (PMID 38833177, 2024). "The pivotal role of Treg cells in tumor resistance and the subsequent enhancement of anti-tumor immunity upon their suppression underscore the therapeutic significance of anti-CTLA-4." (PMID 38473398, 2024). "Recently, many researches have been focused on the combination of anti-PD-1 antibody and other anti-tumor therapies such as anti-CTLA-4 agents, chemotherapy, radiotherapy and so on." (PMID 38833034, 2024). "Targeting VISTA has shown great promise in multiple preclinical models and can decrease myeloid suppression of immune responses as well as induce proinflammatory changes in the tumour microenvironment by mechanisms different from PD-1 and CTLA-4 blockade." (PMID 39060374, 2024). "Antibodies directed at programmed cell death protein 1 receptor (PD1) and its ligand PDL-1 as well as cytotoxic T-lymphocyte-associated protein 4 (CTLA-4) strongly activate the immune system, leading to tumor recognition and destruction." (PMID 38247871, 2024). "For example, CTLA-4, located on the surface of juvenile T lymphocytes, functions to prevent dendritic cells from carrying tumor antigens and stimulating the activation of juvenile T lymphocytes." (PMID 39122457, 2024). "Engineered multifunctional aptamers (P1/C4-bi-apt) improve anti-tumor immune responses by blocking the dual immune checkpoints of CTLA-4 and PD-L1." (PMID 38762484, 2024). "The upregulation of CTLA-4 in activated T cells is a phenomenon observed in tumor tissues (in which activated effector T cells are suppressed) and autoimmune diseases (in which T cells are hyperactivated)." (PMID 38312352, 2024). "The CTLA-4 inhibitors, such as ipilimumab and tremelimumab, have been approved for early-stage clinical trials and have shown promising outcomes in terms of tumor regression and durable responses in patients with advanced HNSCC." (PMID 38474377, 2024). "Future work will need to focus on building a tumor model in the CTLA4 + /- mice treated with ICIs to better recapitulate human disease." (PMID 38355725, 2024). "A relatively large number of PD1-positive lymphocytes was observed in the tumor stroma, whereas fewer CTLA4-positive lymphocytes were distributed in an interspersed manner." (PMID 38514507, 2024). "Tumor cells upregulate CTLA-4 on Tregs, and CTLA-4 competes with CD28 for binding to CD80/CD86 on APCs." (PMID 39534095, 2024). "There is a significant correlation between inhibitory immune checkpoint molecules, i.e., LAG-3 CTLA-4 and PD-Ll, and tumor progression." (PMID 39404378, 2024).